IL1B (interleukin 1 beta)
Diseases named in the same sentence as IL1B in open-access papers (continued):
Sharing a sentence is not in itself a finding about the gene and the disease.
inflammation (continued). "In summary, the present study has demonstrated that the miR-223-NLRP3/IL-1β regulatory circuit plays a protective role in neutrophilic airway inflammation." (PMID 32423405, 2020). "Early studies on patients with SARS showed that elevation of proinflammatory cytokines such as IL-1β, IL-6, IL-12, IFN-γ, IP-10, and MCP-1 was associated with pulmonary inflammation and extensive lung damage." (PMID 32707537, 2020). "Inside the inflammasome, the activated caspase-1 cleaves pro-IL-1β, producing the active form of mature IL-1β, a mediator of lung inflammation, fever, and fibrosis." (PMID 33424586, 2020). "The central nigrostriatal dopaminergic degeneration followed by bowel inflammation is associated with increased TNF-α and IL-1β." (PMID 32731605, 2020). "Elevations of TNF-α and IL-1β—two well-known proinflammatory cytokines—can be verified both in acute and chronic airway inflammation." (PMID 31336570, 2019). "MiR-451 was downregulated in various types of liver inflammation, and subsequent experiments showed that miR-451 regulates liver inflammation via IL1β." (PMID 31816816, 2019). "Chronic airway inflammation is mainly characterized by neutrophil airway infiltrations, and IL-1β is a key mediator of neutrophilic airway inflammation in COPD by playing an important role in initiating and maintaining airway inflammation." (PMID 31275415, 2019). "TNF-α and IL-1β are mostly produced by macrophages and infiltrated monocytes and involved in chronic hepatic inflammation and fibrosis." (PMID 30906791, 2019). "Further investigation using a similar model of lung inflammation indicated that AG was able to reduce the concentrations of pro-inflammatory cytokines IL-1β in BALF and AG suppressed the expression of COX-2 and iNOS in lung tissue." (PMID 31277398, 2019). "Our previous study has demonstrated that PM2.5 induces lung inflammation, represented as increased levels of TP, IL-1β, IL-18, and cell number in the BALFs of BALB/c mice." (PMID 30992001, 2019). "Most pro-inflammatory cytokines (e.g. IFN-γ, TNF-α, and IL-1β) could reduce key TJ-associated proteins such as intracytoplasmic proteins (ZO-1, ZO-2) and transmembrane proteins (occluding and claudin), resulting in disruption of intestinal TJ barrier and the development of intestinal inflammation." (PMID 29538417, 2018). "In the murine subcutaneous air pouch model of acute gouty inflammation, arhalofenate significantly inhibited leukocyte or neutrophil infiltration and production of IL-1β, IL-6, and CXCL1 induced by MSU crystals." (PMID 30189890, 2018). "The early onset of peripheral inflammation response was followed by a late onset of brain inflammation that was demonstrated by level of cytokine IL-1β and ionized calcium binding adapter molecule 1(Iba-1; activated microglial cell marker)." (PMID 28955196, 2017). "In the liver, hepatic macrophages and Kupffer cells recognize Enterococcus and induce interleukin-1 beta (IL1B) secretion contributing to ethanol-induced liver inflammation and hepatocyte damage." (PMID 29038503, 2017). "AS-IV inhibited IL-1β, TNF-α, and nitric oxide (NO) and protected against IL-1β-induced joint inflammation and cartilage destruction in adjuvant-induced arthritis (AIA) rats." (PMID 27872860, 2016). "The “chemical” model was based on chronic esophageal inflammation: IL-1β transgenic (TG) mice received, in their drinking water, 0.2% deoxycholic acid (DCA) for 7 months of treatment." (PMID 27517748, 2016). "Acute brain inflammation after ischemia-reperfusion, as estimated by expression levels of pro-inflammatory cytokines such as interleukin (IL)-1β and tumor necrosis factor alpha (TNF)-α, was significantly suppressed in Angptl2 KO compared to control mice." (PMID 27861531, 2016). "Intrahippocampal injection of PIC induced brain inflammation and in particular increased IL-1β levels as well as facilitated kindling epileptogenesis." (PMID 27955671, 2016).
inflammation (continued). "BML-111 and anti-IL-1β antibody restrains the OVA-induced airway inflammation via downregulation of the TLR2/MyD88/NF-κB pathway." (PMID 25760938, 2015). "It is well established that many inflammatory mediators, such as IL-1β and PGE2, have been implicated in the synovial inflammation and cartilage degradation in OA." (PMID 26538834, 2015). "To more closely mimic the pathophysiological conditions of FLS in an osteoarthritic joint, we employed IL-1β as an inflammation inducing agent that is pivotally involved in joint inflammation and cartilage destruction and induces excessive production of IL-6." (PMID 25312962, 2015). "In mouse models of cigarette smoke-induced pulmonary inflammation, caspase-1 knockout mice had significantly lower levels of IL-1β compared to wild-type mice, which suggests that caspase-1 is critical in pulmonary inflammation." (PMID 26496436, 2015). "In adults and children with suppurative lung disease, airway inflammation is characterised by elevated levels of neutrophils, IL-1β, IL-6 and IL-8." (PMID 26066058, 2015). "The results of the present study demonstrated that IL-1β has a critical role in OVA-induced airway inflammation." (PMID 25760938, 2015). "Previous studies have shown that nerve inflammation and nerve injury caused rapid activation of spinal microglia and elevated expression of TNF-α, IL-1β, and IL-6, which promoted the nociceptive transmission in the spinal cord." (PMID 26064176, 2015). "Weaning induces transient gut inflammation in piglets and the expression levels of some pro-inflammatory cytokines such as IL-1β, IL-6 and TNF-α were up-regulated in newly weaned piglets." (PMID 24609095, 2014). "To assess lung inflammation, we performed total and differential cell counts and quantified levels of IL-1β, TNF-α, KC and MCP-1 by ELISA." (PMID 24495712, 2014). "Allergic asthmatic inflammation is known to be caused by the secretion of a series of Th2 cytokines (IL-4, IL-5, and IL-13) and proinflammatory cytokines (TNF-α and IL-1β)." (PMID 24312355, 2013). "IL-10, IL-1β and COX-2 (encoded by IL10, IL1B, and PTGS2, respectively), are important mediators of intestinal inflammation." (PMID 24194923, 2013). "The role of caspase-1 for intrarenal IL-1β and IL-18 processing and postischemic renal inflammation was documented a decade ago, but the triggers for caspase-1 activation remained enigmatic." (PMID 22046355, 2011). "We show the existence of an IL-1β/IL-23/IL-17 axis which is essential for bleomycin-induced pulmonary inflammation, remodeling and fibrosis." (PMID 21858022, 2011). "LPS can cross the intestinal barrier into the body circulation and reach the lungs, where it exacerbates COPD lung inflammation through the toll-like receptor 4/ nuclear transcription factor-κB (TLR4/ NF-κB) signaling pathway mediating the production of IL-1β, IL-6, IL-17 TNF-α." (PMID 40098933, 2025). "However, while Il6 (interleukin-6) was unaltered, a reduced expression of Il1b (interleukin-1beta), a master pro-inflammatory cytokine in joint inflammation, was significantly reduced in the OA knees of Cxcl9-deficient mice 4 weeks after ACLT." (PMID 40047894, 2025). "These include the downregulation of natural anticoagulants present on the EC surface (TFPI, TM, and EPCR) mediated by TNF-α and IL-1β, as demonstrated in both acute and chronic inflammation, and variation of protein S and upregulation of endothelial adhesive molecule expression." (PMID 39877523, 2025). "Gene expression analysis in the ileum showed that OVX significantly induced intestinal inflammation, as evidenced by increased expression of pro-inflammatory cytokines (Tnf-a, Il-1b, Il-6, and Il-17) and reduced expression of the anti-inflammatory cytokines (Il-10 and Ifng)." (PMID 41466098, 2025). "Microglia activation results in chronic brain inflammation and an increase in proinflammatory cytokines such as TNF-α, IL-1β, and IL-6, which may be closely linked to the pathological features of HE." (PMID 39220284, 2024).
inflammation (continued). "In addition, DiAc-Cp-Mn exerted its anti-inflammatory impact by down-regulating the mRNA expression of iNOS and IL-1β that provoked neuro-inflammation." (PMID 38474469, 2024). "Similarly, another study documented that saxagliptin and vildagliptin alleviated renal inflammation via attenuation of IL-1β, TNF-α as well as iNOS expression." (PMID 37615707, 2024). "Overproduction of IL-1β and IL-18 has been reported to be involved in systemic inflammation." (PMID 38145993, 2024). "In addition, the overexpression of pro-inflammatory cytokines, such as IL-6, TNF-α, and IL-1β, from the macrophages is further involved in the upregulation of inflammatory reactions resulting in inflammation-related diseases." (PMID 39200485, 2024). "Interleukin-1β (IL-1β) is involved in synovial inflammation and synovial fibrosis in RA." (PMID 38966637, 2024). "A classic inflammation panorama is characterized by an early increase of pro-inflammatory cytokines such as IL1β in the head-kidney, and indeed a robust upregulation of il1β was observed in the head-kidney of i.p. injected fish, irrespective of dietary treatment." (PMID 38548769, 2024). "Thus, the targeting of the IL1β hub-hub gene by miR-375 in the turquoise RNA-seq-based module can be predicted to regulate bovine mammary inflammation and IL1β-induced apoptosis." (PMID 37620551, 2023). "Numerous studies have shown the crucial role of IL-1β in synovial inflammation." (PMID 37021049, 2023). "A significant increase in inflammatory cytokines, such as IL-1β and IL-8, an indicator of local vascular inflammation, and pentraxin 3, a molecular marker of endothelial cell dysfunction, were also observed, supporting our experimental findings of dysfunctional CB-ECFCs upon serum deprivation." (PMID 37239042, 2023). "For instance, a large number of NE1 cells were expressed with mature neutrophil markers (e.g., Retnlg, Lcn2, and Asprv1, associated with chronic inflammation), while NE2 cells were highly expressed with pro-inflammatory molecules (e.g., Tnf, Il1b, and Nlrp3, which trigger acute inflammation)." (PMID 37781362, 2023). "The activation of intracellular PRRs in cardiomyocytes leads to inflammasome activation, which converts pro-caspase-1 into the catalytically active protease that is responsible for the production of IL-1β and IL-18, subsequently triggering cardiac inflammation." (PMID 36978920, 2023). "The pro-inflammatory cytokine IL-1β is a key factor in triggering age-related chronic inflammation." (PMID 37760084, 2023). "Together with the general lowering of the inflammation-inducing lipoproteins, among them the Lp(a), an increased resolution of IL-1β-mediated vascular inflammation would allow an additional tool when attempting to reduce the risk of cardiovascular disease in people with an elevated level of Lp(a)." (PMID 37293282, 2023). "In addition, IHC showed that the levels of IL-1β, MCP-1, and TNF-α (associated with intestinal inflammation) decreased by LA-1." (PMID 36325344, 2022). "Similar characteristics were unveiled in a mouse model, as Moraxella-infected mice showed augmented levels of IL-6, IL-1β, IL-17, and tumor necrosis factor α (TNF-α) in lungs, and neutralization of IL-17 and TNF-α was sufficient to accelerate airway inflammation and reduce the risk of AAD." (PMID 36060784, 2022). "A study evaluating neonatal colonic inflammation in rats demonstrated that the increased inflammatory responses observed in adult animals was due to epigenetic changes of the IL-1β promoter that resulted in increased expression following a colitic insult later in life." (PMID 35381031, 2022). "SNPs in PNPLA3, TNF-α, AGTR1, IL-17A, IL-1B, PTPRD, and GATAD2A cause liver inflammation." (PMID 36000237, 2022).
inflammation (continued). "In vivo, treatment of Aspergillus-infected Il1r1–/– mice with anakinra increased the ratio of LC3-II/I and decreased p62, a ubiquitin-binding protein that is selectively degraded by autophagy; inhibited IL-6, IL-17A, IL-1β, and IL-1α production; increased IL-10; and ameliorated lung inflammation." (PMID 34847078, 2022). "To test this, we examined whether G-CSF depletion affected the production of IL-17/IL-1β in neutrophilic airway inflammation." (PMID 36428547, 2022). "However, the detailed signaling pathway for the synthesis of the NLRP3 inflammasome and IL-1β in neutrophil-dominant asthmatic airway inflammation remains to be determined." (PMID 34064821, 2021). "Our results further suggest that regulation of proper mitochondrial dynamics may comprise an approach to counteract excessive brain inflammation promoted by IL-1β." (PMID 33612100, 2021). "Antioxidant activity and inhibition of IL‐1β may help in the prevention of MTX intestinal inflammation." (PMID 34262701, 2021). "Based on previous studies that demonstrated the anti-inflammatory role of dauricine in IL-1β-treated endothelial cells, we established an acute lung injury model induced by LPS to further verify whether dauricine attenuated endothelial inflammation in vivo." (PMID 34925018, 2021). "Moreover, we found that SA attenuated IL-1β secretion in LPS-induced systemic inflammation in mice and reduced lethality from endotoxic shock." (PMID 34571975, 2021). "We have previously shown that Mononuclear Phagocytes-derived IL-1β induces rod photoreceptor cell death during experimental subretinal inflammation and in retinal explants exposed to IL-1β but the mechanism is unknown." (PMID 31900165, 2020). "However, IL-1α has also been reported to be an alarmin and a master cytokine that induces acute lung inflammation via pro-IL-1β synthesis and IL-1β release." (PMID 32316988, 2020). "This study focused on the effects of IL-1β on cartilage gene expression after 2-day treatment, whereas acute joint inflammation could last 2–4 weeks after traumatic injuries (e.g., meniscus tear)." (PMID 30643177, 2019). "We believe that these IL-1β-expressing cells participate in the sensing of injury generated by lung IR and trigger the cascade of events leading to mature IL-1β release, IL-6 production, neutrophil recruitment, and overall lung inflammation." (PMID 29163464, 2017). "TLR9 inhibition could decrease both pancreatic IL-1β expression and lung inflammation in experimental AP15." (PMID 28754974, 2017). "The mature IL-1β is a prototypic multifunctional cytokine that is involved in pulmonary inflammation and could stimulate chemokines and adhesion molecules, such as MCP-1 and MIP-1α for macrophage recruitment." (PMID 28646872, 2017). "In the present study, we hypothesize that ozone might activate the inflammasome to induce release of IL-1β and IL-18 in lung, and the latter in turn increases the production of IL-17A, ultimately leading to neutrophilic airway inflammation." (PMID 26739627, 2016). "In line with this hypothesis, resident hepatic macrophages, Kupffer cells (KCs), in HCV-infected subjects were shown to be the primary cellular source of liver inflammation as they produce significantly high levels of IL-1β upon exposure to HCV10." (PMID 27385120, 2016). "The present study indicated that the inhibitory effects of anti-IL-1β antibody on OVA-induced airway inflammation may be mediated by the inhibitory role of anti-IL-1β antibody on the TLR2/MyD88/NF-κB pathway." (PMID 25760938, 2015). "Additionally, genipin provided protection against flagellin-induced lung inflammation by reducing IL-1β production and neutrophil recruitment." (PMID 26659006, 2015). "Moreover, inflammatory mediators such as IL-1β and PGE2, have been implicated in the synovial inflammation and cartilage degradation in OA." (PMID 26538834, 2015).
inflammation (continued). "Since IL-1β is a proinflammatory cytokine and a mediator of sterile inflammation that acts through IL-1R, it may have a role in the mechanism of lung inflammation and injury induced by mechanical stretch." (PMID 25383882, 2014). "Therefore it seemed that expression of either IL-1α or IL-1β helped controlling acute lung inflammation induced by M. tuberculosis infection." (PMID 25400917, 2013). "In contrast to these findings, both IL-1α−/− and IL-1β−/− mice exhibit defective Th2-mediated resistance to the helminth T. muris, and IL-1α, IL-1β have been reported to be necessary for promoting airway inflammation and particle-induced pulmonary inflammation, respectively." (PMID 23935505, 2013). "Therefore, we measured cytokines (TNFα, IL-1β, IL-6) and a chemokine (KC) in whole lung homogenates as an additional readout for pulmonary inflammation." (PMID 24244609, 2013). "Thus, we conclude that syndecan-4 had limited clinical value as a circulating biomarker of cardiac inflammation and that immunomodulating therapies targeting IL-1β likely will affect the molecular processes that shed syndecan-4 ectodomains play locally in cardiac tissue." (PMID 37189684, 2023). "Activation of IL-1β expression is known to induce lung inflammation by increasing infiltration of neutrophils and macrophages, while IL-1β blockade could ameliorate lung inflammation in high-fat diet-induced obese mice." (PMID 36348343, 2022). "The mature IL-1β is a prototypic multifunctional cytokine that is involved in pulmonary inflammation and could stimulate chemokines and adhesion molecules, such as MCP-1 and MIP-1α for macrophage recruitment, which contributed to CD11b+ cells mobilization in feedback." (PMID 31915037, 2020). "In conclusion, we found that hospitalized, nonsmoking children are highly exposed to ETS and higher ETS exposure levels are associated with higher levels of the cytokine IL-1β, a pro-inflammatory cytokine linked to airway inflammation, regardless of child age, sex, and discharge diagnosis." (PMID 31766400, 2019). "Therefore, we first examined whether TMJ inflammation could concurrently upregulate trigeminal ganglionic IL-1β, COX-2, phospho-CREB, and Nav1.7 expressions." (PMID 29678208, 2018). "Therefore, we infer that these DEmiRNAs might affect the onset of pulmonary inflammation by regulating the cellular response to oxidative stress and IL-1β signaling." (PMID 29593572, 2018). "To test this hypothesis, we used mice deficient in inflammasome-related molecules such as NLRP3, Casp1, and IL-1β, and found that the cardiac glycoside ouabain induces cardiac inflammation and dysfunction via NLRP3 inflammasomes when mice were primed with lipopolysaccharide (LPS)." (PMID 28493895, 2017). "IL-1β and IL-18 are proinflammatory cytokines that contribute to renal immune complex disease, but whether IL-1β and IL-18 are mediators of intrinsic glomerular inflammation is unknown." (PMID 22046355, 2011). "In a separate study, Glutamine decreased the levels of the inflammatory cytokines IL-1β, IL-6 and TNF-α in mice with ulcerative nodular inflammation." (PMID 39367233, 2025). "Further, visceral fat as an active secretory tissue can produce pro-inflammatory cytokines, including IL-1β, IL-6, and TNF-α, adipokines, and other biochemical modulators, which can contribute to systemic and peripheral vascular inflammation." (PMID 41010392, 2025). "By means of pathological staining and ELISA of periapical tissues, this paper revealed the mitigating effect of Pue on periapical inflammation, bone destruction and its suppression on the production of TNF-α, IL-1β and IL-6 in PD mice." (PMID 40312745, 2025). "Chronic inflammation in CKM is characterized by high pro-inflammatory cytokines (e.g., IL-1β, IL-6, TNF-α), which activate NF-κB signaling." (PMID 40227756, 2025).